IL4 (interleukin 4)
Diseases named in the same sentence as IL4 in open-access papers (continued):
Sharing a sentence is not in itself a finding about the gene and the disease.
melanoma (continued). "In a first analysis including the entire cohort of recruited patients (in situ and stage I–IV melanoma patients), the amount of GM‐CSF, IL4, IL‐6, IL‐10, IL‐17A, and TGF‐β detected in serum was independent of the age of the melanoma patients and it did not vary between the sexes." (PMID 32485045, 2020). "We also evaluated the protein amount of a set of 12 cytokines and chemokines, including IL-2, IL-4, IL-5, IL-6, IL-10, IL-12, IL-17A, TNF-α, IFN-γ, MCP-1, MIP-1α, and eotaxin in TIF and plasma samples of C57BL6 mice, engrafted or not engrafted with B16 melanoma cells." (PMID 34604232, 2021).
atherosclerosis (93 papers, 2008 to 2026). A disease characterized by the build-up of fatty material and calcium deposition in the arterial wall resulting in partial or complete occlusion of the arterial lumen. "On the one hand, animal model studies have shown that despite elevated levels of serum lipids, IL-4 deficiency reduced the incidence of atherosclerosis development." (PMID 39944697, 2025). "T-bet deficiency slows atherosclerosis development and increases production of the atheroprotective Th2 cytokines IL-4, IL-5, and IL-10, and IgM antibodies." (PMID 31653058, 2019). "Another study also found that inducing oral tolerance by feeding low-density lipoprotein receptor-deficient mice with HSP65 led to IL-4 (antiatherogenic) production and a reduction in atherosclerosis." (PMID 23304456, 2012). "Pro-inflammatory cytokines such as IL-1β, IL-6 and TNF-α and anti-inflammatory cytokines such as IL-4 and IL-10 provide further insights into the mediators of cellular and systemic responses and have been linked to causal pathways related to atherosclerosis and thrombosis." (PMID 39767790, 2024). "In contrast, other studies demonstrate that high IL-4 and IL-13 production is related to hyperlipidemia, which may increase the risk of developing atherosclerosis." (PMID 37163428, 2023). "This table highlights the high and significant reduction by both protein hydrolysates on TGF-α which is associated with atherosclerosis; also on IL-4, associated with the secretion of TGF-β; and also on the reduction of IL-32α/β/γ, a cytokine that activates NF-κB." (PMID 24891839, 2014). "However in mice deficient in IL4, the archetypical Th2 cytokine, atherosclerosis was less severe than in IL4-sufficient mice." (PMID 22957222, 2012). "Interestingly, the role of IL-4 has been debated, with early studies demonstrating that IL-4 deficiency in a mouse model of atherosclerosis reduced lesion formation, while later studies found a lack of involvement of this cytokine regardless of disease induction method." (PMID 29312440, 2017). "The most abundantly produced, IL-4, with its inhibitory actions against Th1, is considered anti-inflammatory, but in the context of atherosclerosis, its role remains controversial." (PMID 39944697, 2025). "Dupilumab is a fully human monoclonal antibody that has been shown to reduce and downregulate pro-inflammatory cytokines such as IL-4 and IL-13, which are key mediators in AD and also involved in the pathogenesis of cardiovascular diseases and atherosclerosis." (PMID 40922830, 2025). "Th2 cells, known for their anti-inflammatory properties, can delay or potentially reverse atherosclerosis progression, primarily via the secretion of cytokines like interleukin 4 (IL-4), interleukin 5 (IL-5), and interleukin 13 (IL-13)." (PMID 39200308, 2024). "It then associates with IL-4/STAT6 to stimulate plaque macrophages and inhibit atherosclerosis progression." (PMID 38674885, 2024). "IL-4 mRNA expression saw an increase during the progression of atherosclerosis, particularly in the G120 group when juxtaposed with the G30 (MD: −8.26, 95% CI [−11.45 to −5.08], p < 0.001) and G60 groups (MD: −5.27, 95% CI [−8.46 to −2.09], p < 0.001)." (PMID 38610757, 2024). "In contrast to IL-4, Th2 -derived IL-5 and IL-13 antagonize the Th1 response and show a protective effect in atherosclerosis." (PMID 38774746, 2024). "While IL-4 seems detrimental for atherosclerosis progression, it was recently shown to be required for disease resolution." (PMID 36994095, 2023). "At 45 weeks, ApoE−/−/IL-4−/− mice had a significant decrease of 58% and 64% of atherosclerosis located in the aortic arch compared to ApoE−/− and ApoE−/−/IL-12−/− mice, respectively." (PMID 37681883, 2023).
atherosclerosis (continued). "In the setting of atherosclerosis, IFN-γ/LPS-stimulated macrophages are associated with symptomatic and unstable plaques, whereas IL-4-stimulated macrophages are particularly abundant in stable zones of the plaque and asymptomatic lesions." (PMID 36835137, 2023). "CD4+ T helper 2 cells express IL-4 and IL-13, but their impact on atherosclerosis is controversial mainly due to the dubious function of IL-4." (PMID 38138958, 2023). "It is reported that IL-4 played a protective role in atherosclerosis, but some studies demonstrated that IL-4 levels were higher in patients with CAD than normal people." (PMID 35651907, 2022). "The follicular regulatory helper T cells, as a key regulator of atherosclerosis, induce expansion of anti-atherogenic regulatory B cell populations, and regulate lymphangiogenesis through IL-4 secretion in advanced atherosclerosis." (PMID 34735673, 2022). "The main Th2 cytokine is IL-4, which suggests a disease‐promoting effect, while Th2-secreted IL-5 and IL-13 have a protective effect in atherosclerosis patients." (PMID 34915859, 2021). "This suggested that IL-4 is required for atherosclerosis resolution, but collaborates with other factors." (PMID 33720008, 2021). "Taken together, these findings support our conclusion that IL-4 is required for resolution of atherosclerosis of plaques of the type we studied." (PMID 33720008, 2021). "In atherosclerosis, this mechanism primes the response of plaque macrophages to IL-4 that accumulates in plaques during disease progression and together induce resolution of atherosclerosis." (PMID 33720008, 2021). "And in the context of atherosclerosis, IL-4 attenuated atherosclerosis in several different mouse models." (PMID 32655419, 2020). "In atherosclerosis, CD4+ Th2 immune responses are considered to be anti-inflammatory due to the secretion and action of IL-4 or IL-5, linked to B cell activation and antibody production." (PMID 30979943, 2019). "Taken together, ginsenoside Rb1 protected against atherosclerosis by promoting M2 macrophage polarization and limiting intraplaque inflammatory response, which was achieved by increasing the production of IL‐4 and IL‐13 and STAT6 phosphorylation." (PMID 28944992, 2018). "Studies have also reported that IL-13, IL-5 and IL-4 all participate in the pathological process of atherosclerosis, which is the major pathogenesis of CAD12,25–27." (PMID 29670225, 2018). "In atherosclerosis, a similar decrease in iNKT cell numbers and production of IL-4 is observed in established CVD." (PMID 29892305, 2018). "Mice deficient in transcription factors that are required for M2 polarization have accelerated atherosclerosis, while administering type-2 cytokines such as IL-4 to mice protects against atherosclerosis." (PMID 30282904, 2018). "On the other hand, high levels of IL-10 and low levels of IL-4 and IL-8 are protective against atherosclerosis through suppressing macrophages activity." (PMID 29337902, 2018). "With regarding to the influence of IL-4 in atherosclerosis and the primary source(s) of IL-4, the outcomes are controversial." (PMID 29760701, 2018). "IL-4 regulates M2 macrophage polarization via the ERK signaling pathway to protect against atherosclerosis." (PMID 30024944, 2018). "On the contrary, in the development of atherosclerosis, IL-33 markedly increased the levels of IL-4, IL-5, and IL-13, and decreased the level of IFN-γ." (PMID 28423665, 2017). "These include in particular Th1-cell lineage which are pro-atherogenic via the secretion typically of IFN-γ and TNF-α, and Th2-cell lineage secreting IL-4, IL-10 and IL-13 whom their role in atherosclerosis remains controversial, including Th1 and Th2 cells." (PMID 26600018, 2015). "It was assumed that IL-13 would have a similar pro-atherogenic role in atherosclerosis as IL-4, because both cytokines share similar functions by engaging the same receptor complexes." (PMID 23027612, 2012).
atherosclerosis (continued). "On the other hand, others have proposed that PGE2 may cooperate with IL-4 in macrophages to stimulate resolution of atherosclerosis." (PMID 36994095, 2023). "This prompted the formation of a hypothesis about the possible direct participation of IL-4 in the development of atherosclerosis." (PMID 37047399, 2023). "Together, Wnt and IL-4 induce macrophage pro-resolving polarization and atherosclerosis resolution." (PMID 36994095, 2023). "Wnt3a induces prostaglandin E2 (PGE2), which enhances the responsiveness of macrophages to IL-4 and thus may promote the resolution of atherosclerosis." (PMID 37762564, 2023). "The downregulation of IL4, CXCL10, MCP1, TNFα, and estradiol and CSF3 upregulation may mediate the adaptation of adiponectin-deficient males to HFD-induced atherosclerosis." (PMID 38201205, 2023). "A modest ability of IL-4 to augment macrophage superoxide generation as compared to IL-13 is unlikely to have a major physiological impact that would explain opposing roles in cardiovascular disease such as atherosclerosis, hypertension, or MI." (PMID 37949903, 2023). "SARS-CoV-2 infection stimulates secretions of IL-1β, interferon-γ (IFN-γ), IFN-γ-induced protein 10kDa (IP-10), monocytic chemoattractant protein-1 (MCP-1), interleukin-4 (IL-4), IL-6, and interleukin-10 (IL-10), some of which can trigger a cytokine storm and atherosclerosis in a host." (PMID 36289895, 2022). "Next, we further explored whether Th2 cells were another source of IL-4 since Th2 cells were reported to be elevated in the peripheral blood of patients with CP and could regulate M2 macrophage polarization in atherosclerosis." (PMID 35432336, 2022). "The increased IL-4 level might also aggravate the progression of atherosclerosis through its role in monocyte recruitment via the upregulation of VCAM-1 in ECs." (PMID 36497143, 2022). "Thus, the demonstrated molecular mechanism suggests a potential therapeutic strategy to improve the resolution of atherosclerosis after lipid lowering, namely, by co-activation of the IL-4 and PGE2 pathways in plaque macrophages." (PMID 33720008, 2021). "Because we demonstrated that IL-4/13 are important for atherosclerosis resolution, we next examined whether the source of the IL-4/13 is from cells newly recruited in the resolution phase or from cells in the plaques prior to the induction of lipid lowering." (PMID 33720008, 2021). "Collectively, these data indicate that IL-4/13 are needed for atherosclerosis resolution." (PMID 33720008, 2021). "While the role of IL-4 in atherosclerosis remains unclear, other Th2-related cytokines, IL-5, IL-13, and IL-33 appear to exhibit anti-atherogenic properties." (PMID 33805071, 2021). "Thus, resolution of atherosclerosis was similar in WT and Il4-/-Il13-/- recipients, indicating that IL-4/13 production by cells newly recruited is not essential for resolution of atherosclerosis." (PMID 33720008, 2021). "As for atherosclerosis instead, IL-4 roles remain quite elusive as experiments employing genetic deletion of this cytokine in hyperlipidemic animals showed reduced lesion size and inflammation in IL-4 KO animals, while its endogenous administration led to decreased plaque development." (PMID 33770265, 2021). "Researchers have concluded that in atherosclerosis, interleukins such as IL-4, IL-13, and IL-10 activate specific transcription factors (e.g., STAT3 and STAT6, IFN regulatory factor 3, peroxisome proliferator-activated receptor-γ [PPARγ]) in macrophages to encourage inflammation resolution." (PMID 32346605, 2020). "Notably, iNKT cell numbers in peripheral blood seem to increase in the earliest phase of atherosclerosis, accompanied by an increase in IL-4 production, GATA3- and CD69 expression, and increased proliferative capacity." (PMID 29892305, 2018). "Furthermore, the role of TNF-α, IFN-γ, IL-1β, IL-6, IL-8, IL-4 and IL-10 in the pathogenesis of atherosclerosis in carotid artery post-carotid endarterectomy has been documented." (PMID 27271180, 2016).
atherosclerosis (continued). "On the other hand, treatments apt to elicit the expansion of MerTK+ and CD163+ cells (e.g., M2c polarizing agents and IL-4/STAT-6 inhibitors) may help against atherosclerosis progression." (PMID 25972766, 2015). "Furthermore, modulating IL-4, TNF-α, and IL-1β expression suggests an immunomodulatory effect that could reduce atherosclerosis risk." (PMID 40630842, 2025). "Moreover, IL-4 is essential for inhibiting atherosclerosis progression." (PMID 38674885, 2024). "Although IL-4 and IL-5 protect against atherosclerosis, IL-9 may promote atherosclerosis." (PMID 39684449, 2024). "In addition, IL‐4 had been shown to promote the expression of other inflammatory mediators, which might contribute to the development of atherosclerosis." (PMID 38146141, 2023). "However, studies to date have shown that IL-4 deficiency does not affect early atherosclerosis, at least in C57BL/6 mice fed a high-cholesterol diet." (PMID 37047399, 2023). "However, a lack of IL-4 just minimally changes how atherosclerosis develops, IL-5 deficiency, however, has been proven to hasten atherosclerosis." (PMID 37662948, 2023). "We next evaluated whether IL-4/13 content is increased during atherosclerosis resolution." (PMID 33720008, 2021). "However, a growing body of evidence has suggested that IL-4 is pro-atherogenic, and may play a critical role in the progression of atherosclerosis." (PMID 32899258, 2020). "Therefore, the role of IL-4 in atherosclerosis needs to be elucidated." (PMID 28066329, 2016). "Seven core targets-IFNG, CXCL8, TNF, TGFB1, IL2, IL4, and RELA-were identified via network pharmacology, involving key pathways such as lipid-atherosclerosis, AGE-RAGE, and IL-17 signaling." (PMID 40708520, 2026). "These current studies demonstrate that PTPN2 in macrophages inhibits the development of atherosclerosis by regulating IFN-γ, JAK/STAT1, IL-4/6, and NF-κB-induced inflammation." (PMID 37670950, 2023). "However, the limited number of IL-4 cytokines that accumulate in progressing plaques remained constant during the resolution of the disease, indicating that IL-4 collaborates with other factors in the atherosclerosis resolution, namely, STAT6 and Wnt signaling in macrophages." (PMID 37681883, 2023). "The Th2 cytokines IL-4 and IL-13 promote an anti-inflammatory macrophage phenotype through the transcription factor STAT6, and were, thus, proposed as therapies for atherosclerosis." (PMID 36994095, 2023). "IL-4-reporter mice were injected with Pcsk9-AAV and fed WD for 16 weeks to promote atherosclerosis formation." (PMID 33720008, 2021). "To begin to understand the factors upstream of STAT6 needed for atherosclerosis resolution, we examined the requirements for the canonical activators of STAT6, namely IL-4 and IL-13." (PMID 33720008, 2021). "Treatment of Apoe−/− mice with this viral nucleoprotein markedly reduces atherosclerosis and induces a Tr1-type regulatory immune response characterized by enhanced IL-10 but reduced IFN-γ and IL-4 production." (PMID 33805071, 2021). "We investigated the roles of the cytokines IL-4 and IL-13, the classical activators of STAT6, in the resolution of atherosclerosis inflammation." (PMID 33720008, 2021). "We focus on the contribution of cytokine networks encompassing IL-4, IL-6, IL-9, IL-17A, IL-33 but also IFN-γ and TNF-α to vascular dysfunction in atherosclerosis." (PMID 32194407, 2020).